MTOR (mechanistic target of rapamycin kinase)
Diseases named in the same sentence as MTOR in open-access papers (continued):
Sharing a sentence is not in itself a finding about the gene and the disease.
cancer (continued). "CircRNAs also plays an important role in the occurrence, migration and invasion of malignant tumors by affecting Wnt/β-catenin, PI3K/AKT/mTOR and Notch pathways." (PMID 34135756, 2021). "The PI3K/Akt/mTOR signaling pathway is activated in 50–70% of NSCLC and plays an overarching role in all the hallmarks of cancer including evading immune destruction." (PMID 33946744, 2021). "Given that NO promotes glycolysis in neurons and also activates the PI3K/AKT axis in cancer cells, we next examined the role of NO in triggering AKT/mTOR activation and glycolysis in PcrV-primed TAMs." (PMID 34900687, 2021). "Previous studies indicated that EGCG can treat a variety of cancers by inhibiting this signaling pathway, but it was not verified if EGCG exerted mechanism in the treatment of PLGC by targeting PI3K/Akt/mTOR pathway." (PMID 33628319, 2021). "Collectively, these discoveries demonstrate a strong interplay between the PI3K/mTOR and Hippo/YAP pathways and help explain why YAP hyper-activation is observed in some cancers." (PMID 34203293, 2021). "6-shogaol significantly reduced the expressions of p-PI3K, p-AKT, and p-mTOR in OSCC cells; and also inhibited GSK3β downstream of AKT, which plays an important role in the proliferation and apoptosis of cancer cells." (PMID 34644781, 2021). "Polycystin-1 also regulates cell proliferation and cell migration through mTOR and JAK signals in the cancer cell line." (PMID 34064452, 2021). "Thus, it is not surprising that the PI3K/Akt/mTOR pathway may represent a novel potential therapeutic target in cancer, in addition to being a prognostic and diagnostic parameter." (PMID 34681797, 2021). "LMP2A was reported to induce EMT and increases the number of cancer stem-like cells, which is correlated with the activation of the PI3K/AKT/mTOR pathway and up-regulation of EMT-TF SNAI1." (PMID 34407150, 2021). "β-Caryophyllene, β -caryophyllene oxide, and α-humulene, have been also found to induce apoptotic cancer cell death through the regulation of different pathways, such as JAK1/STAT3, NF-kB and PI3K/AKT/mTOR/S6K1." (PMID 34771097, 2021). "We explored the cancer genomic dataset from the cBioPortal to analyze genomic alterations in EGFR, iNOS, mTOR, FGFR, TGFR, and MAP2K1 of 10,953 cancer patients (10,967 samples) from different cancer types." (PMID 33842373, 2021). "LncRNAs also play regulatory roles in cancer-related pathways, such as the Hedgehog, Wnt, Notch, and PI3K/AKT/mTOR pathways, and regulate the plasticity of cancer stem cells." (PMID 34360598, 2021). "Activation of the mTOR signaling pathway upregulates PFKFB3 expression, which suggests a close connection between increased glycolytic flux and cancer development." (PMID 33671514, 2021). "Through the TCGA Pan-cancer Project, copy number variation (CNV), single-nucleotide variation (SNV), and gene expression levels of 40 types of mTOR pathway-related genes and in 32 cancer types were studied." (PMID 34194607, 2021). "Since HPIP modulates cancer cell growth, invasion, epithelial-mesenchymal transition (EMT) and metastasis through regulating various genes, including AKT, ERK, FAK, and mTOR signaling." (PMID 34326318, 2021). "Mechanically, overexpression of ARHGAP25 inactivated AKT/mTOR signaling pathway by regulating Rac1/PAK1 signaling, which was in line with the results from the Gene set enrichment analysis on The Cancer Genome Atlas dataset." (PMID 33994864, 2021). "In order to elucidate the role of CED in cancer therapies, we examined the representative proteins in VEGFR, Akt/mTOR, and MAPK signal pathways by western blot." (PMID 33860036, 2021).
cancer (continued). "ZVI-NP triggered ferroptosis selectively in cancer cells by suppressing NRF2-mediated cytoprotection program, which was attributed to the ZVI-NP-induced disruption of AMPK/mTOR signaling and activation of GSK3β/β-TrCP-dependent degradation system." (PMID 34093872, 2021). "Quercetin promotes apoptosis and autophagy by activating caspase-3 and inhibiting AKT, mTOR, and ERK phosphorylation in cancer cells." (PMID 34381559, 2021). "Mechanistically, it was confirmed that HIF-1α is regulated by both mTOR and ERK pathways in hypoxic cancer cells following vanillic acid treatment." (PMID 34575983, 2021). "Modulation in other signaling events such as mechanistic target of rapamycin kinase (mTOR)/p70S6K, AMP-activated protein kinase (AMPK), PI3K/AKT and p38- MAPK signaling are reported in other cancer models following treatment with BME or pure compounds." (PMID 34765739, 2021). "AKT/mTOR signaling pathway plays an important role in tumorigenesis, and abnormal AKT/mTOR pathways can be found in almost all cancers." (PMID 34527062, 2021). "First, we grouped the 9736 TCGA cancer cohorts into high or low RNA expressions of EGFR, mTOR, NOS2, TGFB1, mTOR, and FGFR1 and compared the survival of cohorts from the two groups." (PMID 33842373, 2021). "Direct anti-cancer effects of metformin target signaling pathways that are involved in cellular growth and proliferation, e.g. the AKT/PKB/mTOR pathway." (PMID 33690729, 2021). "Recent evidence suggested that miRNAs eventually display their functional roles in cancer through the regulation of several signaling pathways, such as AMPK/mTOR, NF-κB, and Wnt/β-catenin pathway." (PMID 34604093, 2021). "TRAIL signaling, the integrated stress response, and the AKT/mTOR/S6 pathway are all known downstream targets of ONC201, and all have regulatory effects on cancer cell adhesion, migration and invasion." (PMID 33557912, 2021). "Among them, Adenosine monophosphate (AMP)-activated protein kinase (AMPK) pathway, mTOR pathway, and Hexosamine Biosynthetic Pathway (HBP) are critical sensors of cellular energy and nutrient status in cancer cells and interact in complex and dynamic ways." (PMID 33828530, 2021). "In summary, this study successfully elucidated the distribution of ancestries in the selection of cancer cell lines using an efficient inference pipeline and subsequent differential drug responses to PI3K/mTOR inhibitors and TKIs in GBM and LGG, respectively." (PMID 34576298, 2021). "The target genes of miR-96 are enriched in cancer-related pathways such as PI3K-Akt signaling pathway and mTOR signaling." (PMID 35047559, 2021). "Given this information, PI3K/mTOR pathway inhibitors have successfully treated primary and metastatic CRC, making this pathway a promising target for clinical cancer treatment." (PMID 34512817, 2021). "We will review the current approaches of targeting mTOR and ERK-1/2 signaling using pharmacological inhibitors and their therapeutic relevance in AA cancer patients." (PMID 33996789, 2021). "In this study, we found that the high expression of LOX is related to the ECM receptor interaction, cancer, Hedgehog, TGF-beta, JAK-STAT, MAPK, Wnt, and mTOR signaling pathways of GSEA." (PMID 34595188, 2021). "Both cancer cells and in vivo tumor xenografts showed that the combined inhibition of PI3K/AKT/mTOR and STAT3 activity enhanced the inhibitory effect of BEZ235 on the proliferation of PTEN-deficient cancer cells." (PMID 33431808, 2021).
cancer (continued). "Our analysis predicted that the target genes and their pathways were mostly related to cancer: MAPK signaling, PI3K-AKT signaling, and mTOR signaling." (PMID 33816220, 2021). "Silibinin attenuated the cancer cell metastasis and epithelial to mesenchymal transition through the autophagy-dependent (AMPK/mTOR) downregulation of the Wnt/β-catenin pathway." (PMID 34681206, 2021). "In particular, PD-L1 expression in cancer cells is regulated by multiple signaling pathways, including NF-κB, MAPK, mTOR, STAT, and cMyc." (PMID 34885221, 2021). "Metformin is a potent anti-tumor compound that suppresses mammalian target of rapamycin (mTOR) via AMP-activated protein kinase (AMPK) upregulation, leading to CP sensitivity of cancer cells." (PMID 33921908, 2021). "Beyond apoptotic proteins, previous studies have reported that Akt/mTOR- and MEK/ERK-dependent signaling pathways regulate cell survival and proliferation in different types of cells, including endothelial cells, cancer cells, and neuronal cells." (PMID 33628381, 2021). "Consistent with our findings, a previous study reported that inhibition of mTOR by rapamycin upregulated EIF4EBP3 and induced cancer cell death." (PMID 34094961, 2021). "The correlation between cancer cell lines and PKD was studied through the mTOR and JAK signaling pathway." (PMID 34064452, 2021). "Our results indicated that UBQLN1 and UBQLN4 played a similar role in some cancer-related pathways, such as apoptosis, cell cycle, EMT, hormone ER, PI3K/AKT, RAS/MAPK, and TSC/mTOR." (PMID 34539785, 2021). "In cancer, activation of PI3K/mTOR signaling results in cell proliferation, prolongs cell survival, shortens the cell cycle and suppresses cell apoptosis." (PMID 34082790, 2021). "The inhibition of multiple molecular pathways such as PI3K/AKT/mTOR, nuclear factor kappa B (NF-kB) and STAT3 have been reported to be involved in its anti-cancer effect even if all the pathways involved remain to be elucidated." (PMID 34832850, 2021). "The database contains 10 common cancer types, 521 compounds, 131 pharmacological pathways, including PI3K/Akt, STAT3, PI3K/Akt/mTOR, Wnt/β-catenin and other signaling pathways." (PMID 34497528, 2021). "The apigenin treatment of melanoma-cancer cells A375 and C8161 promoted growth arrest through the downregulation of p-ERK1/2, p-Akt, and p-mTOR." (PMID 34744708, 2021). "Conclusively, it was noticed that BBR sensitized resistant cancer cells to cisplatin and increased its antigastric cancer properties owing to the inhibition of PI3K/AKT/mTOR signaling." (PMID 34885950, 2021). "Niclosamide induce cell cycle arrest, growth inhibition and apoptosis in cancer cells by targeting multiple signaling pathways such as, Wnt/β-catenin, STAT3, mTOR, Notch signaling pathways and mitochondria metabolic pathways." (PMID 33632240, 2021). "In many cancers, aberrations in the PI3K/Akt/mTOR survival pathway are the most common genomic abnormalities." (PMID 34316328, 2021). "Some cellular signaling pathways, including CSCs (cancer stem cells), the Notch pathway, the EMT (epithelial-mesenchymal transition) and mTOR (mammalian target Rapamycin) can affect the antitumor activity of molecular targeting agents." (PMID 34249768, 2021). "Excessive activation of EGFR activates multiple downstream signaling pathways, such as the MEK/ERK/MAPK, PI3K/AKT/mTOR, and JAK1/STAT3/5 signaling pathways), thereby enhancing the tumorigenesis, progression, and metastasis of various cancers." (PMID 33909822, 2021). "Inhibition of mTOR by cellular energy sensor AMPK activates autophagy, which acts a prosurvival role in cancer cells during ECM detachment." (PMID 35153766, 2021).
cancer (continued). "Thirdly, various cancer-related pathways, including ERBB pathway, MAPK pathway, mTOR pathway, pathways in cancer, TGF-β pathway, and Wnt pathway, were more likely to be activated, leading to poor outcomes." (PMID 34631874, 2021). "In cancers, the activation of PI3K/Akt kinase is a common event and it is known that these kinases are hypersensitive to mTOR inhibitors, including rapamycin." (PMID 34275490, 2021). "Since AMPK negatively controls mTOR activation and mTOR is a downstream effector of AKT, Activation of AMPK is considered to be a possible therapeutic target for cancers that contain high AKT activity." (PMID 34422646, 2021). "Genes such as EGFR, PIK3CA, DROSHA, MDM4, and APC were located inside recurrently aberrant regions, while other known cancer-genes such as NF1, MET and mTOR were identified as cis-genes and located outside the most recurrently altered regions." (PMID 34625038, 2021). "IL-1β and TNF-α, in particular, show a notable overlap of biological activity in cancer and promote tumor angiogenesis by inducing tumor cells to secrete VEGF via the IκB/TSC1/mTOR pathway." (PMID 33925400, 2021). "Increased levels of insulin-like growth factor-1 (IGF-1) and its receptor generally occur in OS and in other cancers, and also activate the PI3K/Akt-mTOR pathway, promoting tumor growth." (PMID 34715874, 2021). "They corresponded to cell fate determination, cell cycle activation, epigenetic modifications, DNA damage response, as well as cancer-related pathways including Wnt/β-catenin, PI3K/AKT/mTOR, Slit2/Robo1, MYC, and ErbB2-ErbB3 axes." (PMID 33747361, 2021). "Previous reports have shown that oncogenic KRAS promotes cancer cell metabolism and proliferation by altering the AKT, MTOR, E2F, and MYC pathways." (PMID 34003553, 2021). "A major reason that highlights the importance of targeting mTOR in RCC relies on the observation that mTOR signaling pathway is activated in RCC, contributing to cancer development." (PMID 35082669, 2021). "The levels of P-eIF2α have been correlated with cell growth, cancer, memory and learning and are stimulated by the integrated stress response (ISR) and the mammalian target of rapamycin (mTOR) pathways (37, –, 39)." (PMID 34006661, 2021). "By contrast, blockade of AMPK by Compound C or shRNA, as well as activation of mTOR by the specific activator MHY1485, significantly reversed the inhibitory effects of FATP5 on cancer cell metastasis." (PMID 34772914, 2021). "Moreover, authors insisted antropin might be a novel molecule with efficacy as dual Akt/mTOR inhibitor, based on their observation that the natural lactone inhibits cancer cell proliferation by promoting apoptosis through down-regulation of AKt/mTOR/GSK-3β/NF-κB signaling pathways." (PMID 33494352, 2021). "The mTOR-mediated inflammatory response can also promote the recruitment of immune cells to TME, resulting in exerting the anti-tumor functions or promoting cancer cell growth, progression, and metastasis." (PMID 35250965, 2021). "TGF-β1/SMAD5, mTOR, NF-κB, RAS/RAF/MEK/ERK, PI3K/AKT, and Wnt/β-catenin pathways are among cancer-related pathways being affected by this lncRNA." (PMID 34671603, 2021). "STC2 and SLC2A1 were both involved in biological behaviors of many cancers, especially in HCC, through the modulation of mTOR signaling pathways." (PMID 34194464, 2021). "Similar effects of apoptosis, cell cycle, EMT, hormone ER, PI3K/AKT, RAS/MAPK, and TSC/mTOR were found between UBQLN1 and UBQLN4 in pan-cancer." (PMID 34539785, 2021). "Recently, in OSCC, another lncRNA CASC9 was found to promote cancer progression through suppressing autophagy-mediated cell apoptosis via inducing AKT phosphorylation and the subsequent activation of the AKT/mTOR pathway." (PMID 34063159, 2021). "↓ mTOR and STAT3 pathway signalling in response to a CDK4/6 inhibitor repressing the stemness of HNSCC cancer cells." (PMID 34137158, 2021).
cancer (continued). "We found that 36 of 40 mTOR pathway genes were differentially expressed by analyzing gene expression in 72 normal tissue samples and 539 KIRC cancer tissues." (PMID 34194607, 2021). "FBXW7 is a critical tumor suppressor that regulates proteasome-mediated degradation of various oncoproteins, such as cyclin E, c-Myc, Mcl-1, mTOR, Jun, Notch and AURKA in human cancer." (PMID 33450701, 2021). "For example, in xenograft models of cancers such as leukemia and breast cancer, different doses of quercetin inhibit the cell cycle and increase programmed cell death by inhibiting the AKT/mTOR signaling pathway." (PMID 34381559, 2021). "Cancer cells and MDSCs express IDO, which activates protein kinase 2 (PK2) and inhibit mammalian target of rapamycin (mTOR) signal, resulting in the hindrance of T cell proliferation and survival." (PMID 33728333, 2021). "In this study, PII3K inhibitor resistant cancer cells were developed by prolonged culturing of cell lines with BEZ235, a dual PI3K and mammalian target of rapamycin (mTOR) inhibitor." (PMID 34681918, 2021). "Like PI3K/AKT/mTOR, Ras/Raf/MEK/ERK cascade is one of the major survival/proliferative signaling pathway that is often constitutively activated in cancer." (PMID 33923896, 2021). "The metformin impact on cancer cell proliferation has been related to adenosine mono-phosphate-activated protein kinase (AMPK) activation, decreased mTOR signaling, and protein synthesis." (PMID 33917520, 2021). "To further explore the antilung cancer mechanism of ZSD, we conducted Human Signal Transduction Pathway Finder PCR Array and found that TRAIL, glypican, IL-3-mediated signaling, Arf6 and mTOR signaling, and PI3K/AKT signaling pathway were mainly enriched." (PMID 33777320, 2021). "Overall, this review article encompasses the significance of racially disparate signaling molecules related to mTOR/ERK1/2 and their potential in developing tailor-made anti-cancer therapies." (PMID 33996789, 2021). "As in many cancer types, PDAC has also been a candidate for targeting the PI3K, including its downstream effectors, such as Akt and mTOR (mammalian Target of rapamycin)." (PMID 34503244, 2021). "Upregulation of ARHGAP25 inhibited cancer cell growth in vivo and in vitro by suppressing glycolysis through inhibition of AKT/mTOR signaling pathway." (PMID 33994864, 2021). "And it was also reported that quercetin exert its anti-cancer effects by promoting apoptosis and autophagy through the modulation of PI3K/Akt/mTOR, Wnt/-catenin, and MAPK/ERK1/2 pathways." (PMID 33746755, 2021). "We observed that in PANC-1 cancer cells, GEM induced the phosphorylation at Ser371 of p70S6 protein, indicating the activation of the mTOR pathway and chemoresistance, whereas, in MDA-MB-231 cells, its modulation was negligible." (PMID 34959348, 2021). "We found that NDD-associated variants had significantly lower RSA values compared with cancer and population variants, especially in the critical FAT and kinase domains, suggesting that low RSA values may be predictive of pathogenicity for NDD-associated MTOR variants, as has been observed in PTEN." (PMID 34197453, 2021). "Multiple cancer-relevant pathways were regulated by significantly differentially expressed miRNAs in TNBC, including PI3K-Akt, cell-cycle, TKIs, PD-1/PD-L1 pathway, mTOR, and JAK-STAT signaling." (PMID 33918859, 2021). "Although some cancers co-express high levels of LARP1 and mTOR, for the majority of cancers they are uncoupled." (PMID 32233986, 2021).